OR4X2 (olfactory receptor family 4 subfamily X member 2)
Description:
Odorant receptor.
Synonyms: OR11-105
Tractability: Antibody: UniProt places it where antibodies can reach, with medium confidence; UniProt predicts a signal peptide or a membrane-spanning region; its Gene Ontology location is reachable by antibodies, with medium confidence.
Gene: Protein-coding gene on chromosome 11 (48,245,104 to 48,246,015, forward strand). Ensembl gene ENSG00000172208.
Subcellular location: Cell membrane
Pathways (Reactome):
Sensory Perception: Expression and translocation of olfactory receptors
Gene Ontology:
Molecular function: olfactory receptor activity; G protein-coupled receptor activity
Biological process: detection of chemical stimulus involved in sensory perception of smell; G protein-coupled receptor signaling pathway
Cellular component: plasma membrane; membrane
Genetic constraint (gnomAD): Loss-of-function variants: 0 observed, 0.0767 expected, observed/expected ratio (o/e) 0, 90% interval 0 to 1.89. That is too few expected variants to judge how well the gene tolerates losing a copy. Missense variants: 554 observed, 380.57 expected, observed/expected ratio (o/e) 1.46, 90% interval 1.36 to 1.56. Synonymous variants: 205 observed, 145.18 expected, observed/expected ratio (o/e) 1.41, 90% interval 1.26 to 1.59.
Homologues: Orthologues: chimpanzee OR4X2 (99% identical), macaque OR4X2 (88% identical), dog OR4X2 (81% identical), mouse Or4x6 (79% identical), mouse Or4x11 (78% identical), rat Or4x6 (78% identical), rat Or4x11 (78% identical), rat Or4x11c (78% identical), rat Or4x13 (77% identical), guinea pig OR4X2 (77% identical), mouse Or4x13 (76% identical), mouse Or4x15 (75% identical), and 2 more. Paralogues in human: OR4X1 (61% identical), OR4S2 (60% identical), OR4B1 (60% identical), OR4C3 (57% identical), OR4A47 (57% identical), OR4C15 (57% identical), OR4C46 (56% identical), OR4C11 (56% identical), OR4C13 (56% identical), OR4C12 (55% identical), OR4A15 (55% identical), OR4C6 (54% identical), and 116 more.
Diseases named in the same sentence as OR4X2 in open-access papers:
OR4X2 is named in the same sentence as 1 disease in open-access papers, as found by Europe PMC text mining. Sharing a sentence is not in itself a finding about the gene and the disease. The quoted sentences say what the papers report.
Dystonia (1 paper, 2021). An abnormally increased muscular tone that causes fixed abnormal postures. "Some genome-wide association studies (GWASs) and replication studies have revealed correlations between single nucleotide polymorphisms (SNPs) of the ARSG, BDNF, NALCN, OR4X2, KIAA1715, and OR4B1 genes and dystonia." (PMID 35273550, 2021).